NFYB (nuclear transcription factor Y subunit beta)
Description:
Component of the sequence-specific heterotrimeric transcription factor (NF-Y) which specifically recognizes a 5'-CCAAT-3' box motif found in the promoters of its target genes. NF-Y can function as both an activator and a repressor, depending on its interacting cofactors.
Synonyms: NF-YB; HAP3; CBF-A; CBF-B
Tractability: Small molecule: a structure with a bound ligand is known. PROTAC: UniProt records ubiquitination sites on it; ubiquitination databases record sites on it; its protein half-life has been measured.
Gene: Protein-coding gene on chromosome 12 (104,117,080 to 104,138,241, reverse strand). Ensembl gene ENSG00000120837.
Subcellular location: Nucleus
Subcellular location (Human Protein Atlas): Nucleoplasm
Pathways (Reactome):
Cellular responses to stimuli: ATF4 activates genes in response to endoplasmic reticulum stress; ATF6 (ATF6-alpha) activates chaperone genes
Metabolism: Activation of gene expression by SREBF (SREBP); PPARA activates gene expression
Gene expression (Transcription): FOXO-mediated transcription of cell death genes
Gene Ontology:
Molecular function: DNA binding; DNA-binding transcription activator activity, RNA polymerase II-specific; DNA-binding transcription factor binding; protein binding; RNA polymerase II cis-regulatory region sequence-specific DNA binding; transcription cis-regulatory region binding; DNA-binding transcription factor activity; DNA-binding transcription factor activity, RNA polymerase II-specific; protein heterodimerization activity; sequence-specific DNA binding
Biological process: positive regulation of transcription by RNA polymerase II; regulation of DNA-templated transcription; regulation of transcription by RNA polymerase II
Cellular component: CCAAT-binding factor complex; nucleoplasm; nucleus; protein-DNA complex; RNA polymerase II transcription regulator complex; chromatin; transcription regulator complex
Genetic constraint (gnomAD): Loss-of-function variants: 7 observed, 15 expected, observed/expected ratio (o/e) 0.47, 90% interval 0.26 to 0.88. The upper end of that interval is the gene's LOEUF score, 0.88, which puts it in group 3 of 6, group 1 being the genes least tolerant of losing a copy. Missense variants: 81 observed, 176.13 expected, observed/expected ratio (o/e) 0.46, 90% interval 0.38 to 0.55. Synonymous variants: 59 observed, 56.84 expected, observed/expected ratio (o/e) 1.04, 90% interval 0.84 to 1.29.
Homologues: Orthologues: pig NFYB (99% identical), chimpanzee NFYB (99% identical), macaque NFYB (99% identical), mouse Nfyb (99% identical), dog NFYB (99% identical), rabbit NFYB (99% identical), guinea pig NFYB (95% identical), rat Nfyb (95% identical), tropical clawed frog nfyb (92% identical), zebrafish nfyba (81% identical), zebrafish nfybb (80% identical), Drosophila melanogaster Nf-YB (39% identical). Paralogues in human: DR1 (26% identical), FAM47E (15% identical).